IRS1 (insulin receptor substrate 1)
Diseases named in the same sentence as IRS1 in open-access papers (continued):
Sharing a sentence is not in itself a finding about the gene and the disease.
Insulin resistance (continued). "DG are involved in cellular signaling, including the PKCθ-induced inhibitory phosphorylation of IRS1, thereby acting as second messengers leading to insulin resistance." (PMID 38473949, 2024). "This serine phosphorylation of IRS-1 inhibits its ability to propagate the insulin signal effectively, leading to further impairment of glucose uptake and exacerbation of insulin resistance." (PMID 39519193, 2024). "Animal studies have revealed that neutrophil elastase in adipocytes can diminish insulin receptor substrate 1 and inhibit insulin-induced AKt protein kinase phosphorylation, consequently elevating insulin resistance levels." (PMID 38890369, 2024). "Studies have shown that HFD feeding leads to increased phosphorylation of insulin receptor substrate 1 (IRS1), therefore inhibiting the IR/IRS-1 interaction and ultimately causing insulin resistance." (PMID 39064674, 2024). "For example, liver-specific Irs1/Irs2 double-knockout mice show insulin resistance in adipose tissue, which is relieved when hepatic FoxO1 is deleted." (PMID 38967989, 2024). "We further investigated the mechanism of 1 mediating impaired inflammation and oxidative stress, using immunoblotting, since several reports indicate PKC is also involved in enhancing insulin resistance by increasing IRS1 serine phosphorylation." (PMID 39125053, 2024). "Mitochondrial fission, which causes mitochondrial dysfunction, decreases the activation of p38 MAPK, increases the activity of IRS-1 and AKT and causes insulin resistance." (PMID 38397072, 2024). "HSP72 inhibits the activation of stress kinases such as c-jun-NH2-terminal kinase (JNK), which promotes insulin resistance by inhibiting the phosphorylation of insulin receptor substrate 1 (IRS-1), thereby regulating T2DM." (PMID 38673794, 2024). "Similar findings have been demonstrated with the administration of a butyric acid derivative attenuating LPS-induced inflammation and insulin resistance with decreased phosphorylated IRS-1 measured in mouse adipocytes." (PMID 38257161, 2024). "ROS can inhibit IRS1 activation, thereby impairing insulin signaling and aggravating insulin resistance." (PMID 39728000, 2024). "In particular, resistin, leptin, and PAI-1 induce insulin resistance by interfering with the expression of insulin receptor substrate-1 (IRS-1), negatively impacting insulin signaling in PLTs." (PMID 39858414, 2024). "High glucose concentration induced insulin resistance, as shown by decreased insulin induced tyrosine phosphorylation of insulin receptor substrate-1 (lane 4) when compared to normal glucose (lane 2)." (PMID 39119463, 2024). "Our results also demonstrate that the loss of BVR-A is an early event during the development of brain insulin resistance in T2D, since it manifests before the accumulation of canonical hallmarks of insulin resistance, i.e., inhibited IRS1." (PMID 38843768, 2024). "The direct mechanism of inducing insulin resistance in skeletal muscle cells is the serine phosphorylation of insulin receptor substrate 1 (IRS-1) by the stress-response kinases (JNK, p38, and PKC) activated by ROS." (PMID 38892574, 2024). "Previous studies showed that homoplantaginin suppressed PA-induced inflammation and insulin resistance in the endothelial cells by modulating the IKKβ/IRS-1/pAkt/peNOS pathway." (PMID 39765815, 2024). "The inflammatory cascade can downregulate glucose transporters and insulin-related molecules (such as GLUT4, cyclin A, cyclin E, and IRS-1), leading to elevated blood glucose and insulin resistance in patients with T2DM." (PMID 38396669, 2024). "Most studies investigating the relationship between resistin and insulin resistance propose that resistin is positively correlated with insulin resistance by inhibiting the IRS-1/PI3K/AKT pathway." (PMID 40302954, 2024).
Insulin resistance (continued). "In vitro, betaine reversed insulin resistance by increasing insulin-stimulated tyrosine phosphorylation of IRS1 and activation of downstream proteins in the insulin signaling cascade in insulin resistant primary human hepatocytes." (PMID 39119463, 2024). "In this study, both LF and GFL supplementation attenuated hepatic insulin resistance demonstrated by reduced p-IRS-1(Ser) to IRS-1 ratio in diabetic mice." (PMID 39796441, 2024). "If this phenomenon persists with time, the inhibition of IRS1 and the development of insulin resistance occurs." (PMID 38843768, 2024). "Serine kinases, such as c-Jun-N-terminal Kinase (JNK) and inhibitor of nuclear factor kappa-B kinase subunit beta (IKKβ), contribute to insulin resistance through phosphorylation of IRS-1." (PMID 38257161, 2024). "One of the hallmarks of insulin resistance is increased phosphorylation of IRS1 protein at Ser307, which inhibits the insulin receptor signaling cascade." (PMID 39268230, 2024). "Evidence indicates that PKC plays a pivotal role in enhancing insulin resistance by increasing serine phosphorylation of IRS-1." (PMID 39125053, 2024). "This phosphorylation event impeded the interaction between IRS-1 and the insulin receptor, thereby establishing a mechanistic basis that partially elucidated the development of insulin resistance in the context of obesity." (PMID 38248343, 2024). "Inflammatory factors such as IL-6 induce insulin resistance by enhancing serine/threonine phosphorylation of insulin receptor substrate-1 (IRS-1)." (PMID 38529045, 2024). "Meanwhile, oleanolic acid attenuated adipose tissue insulin resistance induced by fructose over-consumption in rats via IRS-1/PI3K/AKT signaling pathway." (PMID 38799166, 2024). "TNF-α is a potent activator of NF-κB, which induces insulin resistance through serine phosphorylation of the insulin receptor substrate-1 (IRS1)." (PMID 38164478, 2024). "TNF-α, ChAs, and growth hormones induce insulin resistance by inhibiting tyrosine kinases and the tyrosine phosphorylation of IRS-1." (PMID 39682557, 2024). "In line with the current study, different plant metabolites were reported to alleviate insulin resistance by regulating the IRS1/PI3K/AKT signaling pathway." (PMID 39795155, 2024). "In MASLD, the increased activation of JNK leads to inhibitory phosphorylation of insulin receptor substrate 1, resulting in insulin resistance and hyperinsulinemia." (PMID 39600928, 2024). "In summary, current research has demonstrated that MG53 mediates the degradation of IRS-1 via ubiquitination, resulting in systemic insulin resistance and ultimately metabolic syndrome." (PMID 38681139, 2024). "The level of p-IRS-1/IRS ratio indicating insulin resistance was significantly higher in the DMC group than in other groups." (PMID 39796441, 2024). "Dysfunctional IRS-1/2 signaling, resulting from chronic neuroinflammation and the toxicity of Aβ oligomers, is considered a key element in the development of insulin resistance in AD." (PMID 39769243, 2024). "In vitro, betaine reversed insulin resistance in primary human hepatocytes by increasing insulin-stimulated tyrosine phosphorylation of IRS1 and of Akt." (PMID 39119463, 2024). "TNF can inhibit insulin-induced tyrosine phosphorylation of insulin receptor substrate 1 (IRS1) and glucose uptake, and promote degradation of the GKAP42 protein in adipocytes, thus causing T2DM and insulin resistance." (PMID 36747287, 2023). "It is noteworthy that inflammatory cytokines promote insulin resistance, increasing the Ser302 phosphorylation of IRS1." (PMID 37298533, 2023). "Central insulin resistance can be measured through abnormalities in insulin signalling mediated by insulin-receptor substrate-1 (IRS-1)." (PMID 37536279, 2023). "Cblb is an ubiquitin E3 ligase that specifically degrades IRS1 protein and induces insulin resistance." (PMID 37576807, 2023).
Insulin resistance (continued). "The paramount postulated mechanism of the development of insulin resistance is the reduced phosphorylation response of IRS-1 and IRS-2 (insulin receptor substrate-1 and -2)." (PMID 37445466, 2023). "Previous targeted studies have associated insulin resistance with defects in proximal insulin signaling proteins, including AKT, IRS1/2, and the insulin receptor." (PMID 36808134, 2023). "IKK and JNK1 phosphorylate IRS1 and IRS2 on the serine residue, which causes activation of the gene linked to insulin resistance and inflammation." (PMID 37241737, 2023). "More specifically, increased phosphorylated IRS1 (p-IRS1) causes decreased expression of Protein kinase B (AKT), and phosphoinositide 3-kinase (PI3K) allows for the progression of insulin resistance." (PMID 37047241, 2023). "Specifically, the IRS-1 phosphorylation pattern of NDEs reflecting insulin resistance was increased five-fold immediately after intervention (p = < 0.001)." (PMID 37238988, 2023). "The key mechanism of insulin resistance is dysfunction of the insulin signaling, while the IRS1/AKT/FOXO1 signaling pathway plays a vital role." (PMID 38034083, 2023). "PF suppresses lipid accumulation and alleviates insulin resistance by regulating the Rho kinase/IRS-1 pathway in palmitate-induced HepG2Cells." (PMID 37324475, 2023). "Deletion of liver IRS1 and 2 in mice induces systemic insulin resistance, leading to diabetic symptoms that include hyperglycemia and hyperinsulinemia." (PMID 37960324, 2023). "The disruption of IRS1 signaling is a key and common mechanism in developing insulin resistance in population and laboratory studies." (PMID 37780625, 2023). "There is evidence that ROCK interacts with the insulin receptor substrate-1 (IRS-1) and impairs insulin signaling in skeletal muscle, and that the resulting increased insulin resistance leads to the development of T2DM." (PMID 38169604, 2023). "In the context of obesity, an excessive intracellular Ca2+ level prevents the membrane localization of the PIP-binding proteins AKT, IRS1, and PLCδ via Ca2+-PIPs, contributing to insulin resistance and other metabolic diseases." (PMID 37524877, 2023). "The level of NDEs and their status of IRS-1 phosphorylation, known to reflect insulin resistance, were assessed." (PMID 37238988, 2023). "Another mechanism leading to the development of insulin resistance by overexpression of the SOCS protein was through reduction in the tyrosine phosphorylation of IRS1 and IRS2 required for insulin transduction." (PMID 37529379, 2023). "ACNs prevent the stimulation of JNK and NF-B, which lowers the phosphorylation of IRS-1 serine residues and improves insulin resistance." (PMID 37241737, 2023). "Polymorphism in “ectoenzyme nucleotide pyrophosphate phosphodiesterase 1” (ENPP1 or PC1) and in “insulin receptor substrate-1” (IRS1) genes, which are related to insulin resistance, have also been described in NAFLD patients." (PMID 36976456, 2023). "Insulin resistance is mainly due to the interference in normal insulin signaling by decreasing the expression of insulin receptors, IRS1 and IRS2." (PMID 37014444, 2023). "While, among the common downregulated Pparg target genes, both Irs1 and Myc are involved in insulin signaling, revealing the Pparg-mediated insulin resistance in females during ovarian insufficiency." (PMID 36768630, 2023). "Increased activity of mTORC1 induces insulin resistance by phosphorylating insulin receptor substrate 1 (IRS-1), thus inhibiting insulin-stimulated glucose uptake." (PMID 38068805, 2023). "Inflammation and insulin resistance are mediated by the inhibition of serine phosphorylation of IRS-1 by JNK." (PMID 37396948, 2023). "In general, insulin resistance is defined as the reduced response to insulin by target cells, due to reduced IR levels and/or activation or increased IRS1 inhibitory phosphorylation that finally results in impaired glucose uptake and cell metabolism." (PMID 36670973, 2023).
Insulin resistance (continued). "IL-1 is demonstrated to activate the IKK/NF-кB pathway in the skeletal muscle, decrease IRS-1 activity, and enhance skeletal muscle insulin resistance." (PMID 37876013, 2023). "We also analyzed the levels and the phosphorylation of the IRS1 protein, an important player in controlling insulin receptor signaling and in promoting insulin resistance." (PMID 37298533, 2023). "IL-6 induces insulin resistance by downregulating insulin receptor substrate-1 (IRS-1) phosphorylation and transcription and by upregulating suppressor of cytokine signaling 3 (SOCS3), which inhibits insulin receptors." (PMID 37893164, 2023). "In these studies, obese rodents and human adipose tissue have demonstrated higher levels of pro‐inflammatory cytokines such as TNF‐α, which can promote insulin resistance by inactivating the IRS‐1 molecule." (PMID 37329278, 2023). "Subsequently, insulin resistance can be promoted through decreased action of the IRS1/PI3K/AKT pathway." (PMID 37106780, 2023). "CNB-001 restored PA-induced insulin resistance and impaired insulin signaling by improving insulin-stimulated glucose uptake and increasing insulin-stimulated p-IR, p-IRS-1, and p-AKT expression levels." (PMID 37762669, 2023). "mRNA expression of IRS-1 was found lower in the livers of HFD/STZ-induced diabetic rats while the treatment of AMEBB and Berb upregulated mRNA expression of IRS-1, a key contributor in insulin resistance." (PMID 37089941, 2023). "The study also found that Neuron-EVPs have a higher concentration of insulin receptor substrate-1 (IRS-1) associated with suicidality and anhedonia, confirming previous research linking MDD to insulin resistance, which also impacts glutamate levels." (PMID 37266331, 2023). "In both male and OVX females, heart specific IRS1/2 double knockout induces cardiac insulin resistance and diabetic cardiomyopathy." (PMID 36942499, 2023). "Chronic hyperinsulinemia with overnutrition activated the mTOR/S6 kinase pathway and enhanced phosphorylation of insulin receptor substrate 1 (IRS-1) serine to induce hypothalamic insulin resistance." (PMID 37867511, 2023). "Other than cognitive dysfunction, the abnormal expression of IRS1 is also related to T2D and hippocampal insulin resistance." (PMID 36979171, 2023). "Of note, adipose-derived TNF-α and IL-6 are crucial adipokines that suppress adipocyte insulin sensitivity and even lead to insulin resistance by attenuating insulin receptor-substrate 1 (IRS-1), which is a necessary component of insulin signaling." (PMID 37555019, 2023). "High miR-222 expression in mouse adipose tissue-derived exosomes can aggravate insulin resistance in the liver and skeletal muscle of obese mice on a high-fat diet by suppressing insulin receptor substrate 1 (IRS1) expression." (PMID 37791070, 2023). "It is thought that GCE lowers insulin resistance by the activation of insulin receptor substrate-1 via inhibiting c-Jun N-terminal kinase phosphorylation." (PMID 38035358, 2023). "Insulin resistance in the skeletal muscle in PCOS is mediated through impaired IRS-1 expression and phosphorylation, post-receptor signaling defect, and abnormal GLUT4 translocation." (PMID 36675485, 2023). "Decreased the fasting blood glucose level, improved oral glucose tolerance, alleviated insulin resistance; activated IRS1, PI3K, and GLUT4, inhibited JNK1/2; regulated the IRS1/PI3K and JNK signaling." (PMID 36671814, 2023). "The impaired downstream signaling of IRS1/2 appears to be a key component of hepatic insulin resistance, yet studies on the correlation of IRS1 and 2 expression to MASLD have yielded contradictory results." (PMID 37842470, 2023). "It was reported that IL-1β disrupts insulin signaling and leads to insulin resistance in hepatocytes via decreasing IRS-1 expression." (PMID 37876013, 2023).
Insulin resistance (continued). "Prolonged insulin exposure induced insulin resistance in primary human skeletal muscle-derived cells (HMDCs), as characterized by blunted IRS-1 phosphorylation (Tyr612) and Akt (Ser473) phosphorylation in response to an acute insulin stimulation." (PMID 36942499, 2023). "Increased OGT in the liver has been reported to inhibit the expression of insulin signaling genes, such as IRS1 and Akt, contributing to insulin resistance." (PMID 36768465, 2023). "During insulin resistance, impairment of insulin receptor substrate-1(IRS-1) results in the inability of GLUT4 transporter to translocate to the surface of the membrane to facilitate glucose entry into the cell." (PMID 38096150, 2023). "We previously reported on the accumulation of markers of brain insulin resistance, such as reduced IR protein levels and increased IRS1 inhibition, in the brain of young DS individuals before AD development." (PMID 36670973, 2023). "These molecules can exacerbate systemic insulin resistance and contribute to cardiac insulin resistance mediated by insulin receptor substrate protein-1 (IRS-1) serine (Ser) phosphorylation." (PMID 37892985, 2023). "This, in turn, leads to IL-1β and IL-18 secretion and subsequent insulin resistance through serine phosphorylation of IRS-1 and impairment of insulin signaling." (PMID 37372020, 2023). "Immunoblotting showed lower protein levels of Akt/mTOR and phosphorylated insulin receptor substrate 1 (p-IRS1) in ApoE4 mice than in ApoE3 mice, suggesting that ApoE4 led to energy metabolism dysfunction and insulin resistance." (PMID 36720919, 2023). "Phosphorylation of IRS-1ser307 is associated with decreased insulin-stimulated IRS-1 tyrosine (IRS-1tyr) phosphorylation and insulin resistance." (PMID 37432173, 2023). "Phosphorylation of IRS-1ser307 residue in the nearing of the phosphotyrosine-binding (PTB) domain by the insulin resistance inducer decreased the binding force between IR and IRS1 and disassociated the coupling of IRS-1 signal transduction to PI3K." (PMID 37432173, 2023). "JNK promotes insulin resistance by inhibiting the phosphorylation of insulin receptor substrate 1 (IRS-1), a key protein in the insulin signaling cascade." (PMID 37238736, 2023). "It is reported that TNF-α has been linked to signaling pathway of insulin impairment by increasing serine phosphorylation of IRS-1, which inhibits activity of tyrosine kinase resulting in impaired downstream signaling and development of insulin resistance." (PMID 37089941, 2023). "The results indicate that combinational use of ARVs upregulates inflammasome activation and promotes insulin resistance through dysregulation of the IRS1/PI3K/AKT insulin signaling pathway." (PMID 37047241, 2023). "For example, ginsenosides have been shown to improve insulin resistance and glucolipid metabolism through triggering IRS-1/PI3K/AKT as well as AMPK signaling pathways." (PMID 37465522, 2023). "The serine phosphorylation of the insulin receptor substrate-1 (IRS1) in an NK/IKK-dependent fashion results in insulin resistance induced by pro-inflammatory cytokines." (PMID 37241737, 2023). "According to the available findings, phosphorylation of IRS1 is strongly correlated with insulin resistance." (PMID 36333974, 2023). "In its downstream pathway, GSF can not only inhibit insulin resistance induced by inflammatory cytokines but can also regulate glucose and lipid metabolism by directly or indirectly increasing IRS-1 activity." (PMID 37089916, 2023). "Specifically, it has been reported that TNFα inhibits the proper phosphorylation of IRS-1, favouring the development of insulin resistance." (PMID 38132872, 2023). "In skeletal muscle, mTOR over-activation can generate insulin resistance through the degradation of IRS-1 via S6K1, leading to a reduced glucose uptake." (PMID 37298274, 2023).